RNU6-1072P (RNA, U6 small nuclear 1072, pseudogene)
Gene: Small nuclear RNA gene on chromosome 1 (12,922,554 to 12,922,660, forward strand). Ensembl gene ENSG00000207434.
Homologues: Orthologues: macaque U6 (86% identical), rabbit U6 (83% identical), mouse Gm22950 (82% identical), dog U6 (81% identical), guinea pig U6 (81% identical), rabbit U6 (75% identical). Paralogues in human: RNU6-771P (100% identical), RNU6-1323P (92% identical), RNU6-25P (88% identical), RNU6-35P (88% identical), RNU6-1 (87% identical), RNU6-1316P (87% identical), RNU6-2 (87% identical), RNU6-29P (87% identical), RNU6-338P (87% identical), RNU6-3P (87% identical), RNU6-48P (87% identical), RNU6-4P (87% identical), and 1284 more.